CRP (C-reactive protein)
Diseases named in the same sentence as CRP in open-access papers (continued):
Sharing a sentence is not in itself a finding about the gene and the disease.
chronic obstructive pulmonary disease (continued). "COX univariate analysis showed that mortality within 6 months was associated with leucine > 174 μM or <109 μM, age, APACHE II and SOFA scores, chronic obstructive pulmonary disease, and levels of C-reactive protein, cholesterol, albumin, prealbumin, and transferrin." (PMID 35035612, 2022). "The Cox proportional hazards model, in covariate balanced population analysis, showed that highly predictive variables for ICU mortality were age, body mass index, high levels of C-reactive protein, procalcitonin, ferritin, D-dimers, and the presence of chronic obstructive pulmonary disease." (PMID 35135588, 2022). "Either after adjusting for age and chronic obstructive pulmonary disease or after adjusting for age, chronic obstructive pulmonary disease, C-reactive protein, cholesterol, albumin, pre-albumin, and transferrin, leucine > 174 μM remained an independent predictor of mortality within 6 months." (PMID 35035612, 2022). "Furthermore, the use of a point-of-care CRP level >40 mg/dL significantly increases the predictive accuracy of treatment failure among patients with exacerbated mild to moderate chronic obstructive pulmonary disease." (PMID 33606735, 2021). "However, due to the small sample size of the existing studies, the clinical value of CRP in guiding the use of acute exacerbation of chronic obstructive pulmonary disease (AECOPD) antibiotics is insufficient." (PMID 32702869, 2020). "The current scoring tool is able to clarify the combination of surgical factors and patient factors by focusing on active smoking, CRP levels and intraoperative parameters, such as anastomotic type, reconstruction route and the presence of intraoperative cardiac arrhythmia." (PMID 32252738, 2020). "Moreover, CTRP5 was positively correlated with CRP in subjects with chronic obstructive pulmonary disease." (PMID 29964236, 2019). "Chronic Obstructive Pulmonary Disease (COPD) is associated with evidence of systemic oxidative stress, activation of circulating inflammatory cells and increased plasma level of proinflamatory cytokines which include C-reactive protein (CRP)." (PMID 27275236, 2015). "In clinical studies, CRP is a biomarker of declining lung function and a determinant of survival in respiratory illnesses such as COPD (Chronic Obstructive Pulmonary Disease) and interstitial lung disease." (PMID 39596365, 2024). "Cox regression analysis revealed that albumin was independently associated with mortality (hazard ratio: 2.48) after adjusting for sex, heart failure, chronic obstructive pulmonary disease (COPD), and CRP levels." (PMID 36267156, 2022). "This study aims to explore the correlation between high-sensitivity C-reactive protein (hs-CRP), interleukin-6 (IL-6), interleukin-10 (IL-10), endothelin-1 (ET-1), and chronic obstructive pulmonary disease combined with pulmonary hypertension (COPD-PH)." (PMID 35186226, 2022). "Biomarkers of systemic inflammation such as C-reactive protein (CRP) and fibrinogen have been associated with lower FEV1 and FVC, chronic obstructive pulmonary disease (COPD) and asthma." (PMID 32518239, 2020). "Elevated blood levels of pro-inflammatory markers, such as CRP and IL-6, are found in patients with chronic obstructive pulmonary disease (COPD)." (PMID 31151190, 2019). "Notably, studies have demonstrated that a high TyG index correlates with elevated C-reactive protein (CRP) levels in patients with chronic obstructive pulmonary disease (COPD), suggesting a shared inflammatory pathway." (PMID 40421215, 2025). "In this retrospective cohort of 1000 ICU patients with chronic obstructive pulmonary disease (COPD), we assessed the prognostic relevance of inflammatory and nutritional biomarkers, focusing particularly on serum C-reactive protein (CRP), albumin, glucose, creatinine, and lactate levels." (PMID 41010314, 2025).
chronic obstructive pulmonary disease (continued). "Additionally, conditions associated with UPE following MICS include diabetes, chronic obstructive pulmonary disease (COPD), right ventricular dysfunction, pulmonary hypertension, and elevated perioperative C-reactive protein levels." (PMID 39768577, 2024). "The age, renal insufficiency, chronic obstructive pulmonary disease (COPD), use of antipsychotics, lactate dehydrogenase (LDH), and C-reactive protein are used to build a nomogram for POD with an AUC of 0.71." (PMID 38267405, 2024). "ALT, alanine aminotransferase; BMI, body mass index; BUN, blood urea nitrogen; COPD, chronic obstructive pulmonary disease; CRP, C-reactive protein; eGFR, estimated glomerular filtration rate; interquartile range, IQR; WBC, white blood cells." (PMID 39650981, 2024). "The resulting multivariate model had a c-statistic of 0.86, and key parameters were age, CRP, LDH, and presence of ischaemic heart disease or chronic obstructive pulmonary disease." (PMID 36103084, 2023). "In addition, a study base on patients with chronic obstructive pulmonary disease (COPD) also observed that Fluvastatin and Atorvastatin are more effective in reducing C-reactive protein and pulmonary hypertension." (PMID 36683706, 2022). "Another research team investigated the effect of 6 months of nasal CPAP therapy on CRP levels in patients with overlap syndrome, i.e., the coexistence of OSA with chronic obstructive pulmonary disease (COPD)." (PMID 35273744, 2022). "The Global Initiative for Chronic Obstructive Lung Disease (GOLD) strategy documents suggest that antibiotics usage should be based on clinical signs of infection, blood CRP level, and blood procalcitonin level." (PMID 35307030, 2022). "The value of blood CRP and peripheral blood WBC counts alone or in combination in the diagnosis of acute exacerbations of chronic obstructive pulmonary disease." (PMID 35024012, 2021). "By univariate Cox analysis, chronic obstructive pulmonary disease (COPD), post procedural CRP level, and 72-hours post procedural AKR were significant predictors of CV mortality." (PMID 34375346, 2021). "This study aimed to investigate the relationship between nutritional status, mean platelet volume (MPV), C-reactive protein (CRP)-to-albumin ratio (CAR), and mortality in geriatric chronic obstructive pulmonary disease (COPD) patients." (PMID 35070560, 2021). "HBP, CRP, WBC, neutrophils, and other inflammatory indicators can be used as biological indicators of acute exacerbation of chronic obstructive pulmonary disease." (PMID 35024012, 2021). "Plasma concentrations of CRP in patients with HFpEF positively correlated with NT-proBNP, the prevalence of chronic obstructive pulmonary disease (COPD), endothelin-1 concentration, aldosterone concentration, body mass index (BMI) and the overall number of comorbidities." (PMID 31705352, 2020). "Several studies are ongoing, testing the usefulness of CRP measurements as an aid to shorten the duration of therapy in adult patients having sepsis, community-acquired pneumonia or exacerbation of chronic obstructive pulmonary disease (COPD)." (PMID 23837559, 2013). "The purpose of the study was to determine the relationship between high sensitivity C-reactive protein (hs-CRP) levels and prognostic factors in chronic obstructive pulmonary disease." (PMID 24073993, 2013). "Hence, in patients with chronic obstructive pulmonary disease, elevated CRP levels have been found to be associated with reduced FEV1, exercise capacity, metabolic and functional impairment, hospitalization, all-cause and COPD mortality." (PMID 23676005, 2013). "Similarly, in hospitalized patients with acute exacerbations of chronic obstructive pulmonary disease (AECOPD), CRP levels showed significant correlations with nutritional risk." (PMID 40871652, 2025).
chronic obstructive pulmonary disease (continued). "Furthermore, a composite score (CIBLE score) that includes age, CRP, temperature, chronic obstructive pulmonary disease (COPD) and eosinophils/granulocytes count ratio, was found to predict bacterial infection when > 87, with a 72% sensitivity and a 77% specificity (190 patients, 73.5 (18.2) y/o)." (PMID 38093181, 2023). "Similarly, in another study in 13 patients with stable chronic obstructive pulmonary disease, there was a significant correlation of NLR with CRP (r = 0.309, P < 0.001)." (PMID 35601749, 2021). "For example, C-reactive protein serum levels in chronic obstructive pulmonary disease (COPD) patients are roughly twice that of non-smoking patients (~4.0 mg/L vs 1.9 ml/L)." (PMID 34959590, 2021). "Traits such as cerebrovascular disease, electrolyte imbalance, hypothyroidism, congestive heart failure, neurological diseases, chronic obstructive pulmonary disease (COPD), and bipolar affective disorders also had positive genetic correlations with CRP levels (P < 0.05)." (PMID 34386016, 2021). "COPD: chronic obstructive pulmonary disease; IQR: interquartile range; CRP: C-reactive protein." (PMID 34878066, 2021). "C-reactive protein (CRP) point-of-care testing can reduce antibiotic use in patients with acute exacerbation of chronic obstructive pulmonary disease (AECOPD) in primary care, without compromising patient care." (PMID 33657007, 2021). "BMI: body mass index; COPD: chronic obstructive pulmonary disease; CNS: central nervous system; Scr: serum creatinine; WBC: white blood cells; CRP: C-reactive protein; APACHE II: acute physiology and chronic health evaluation II; SOFA: sequential organ failure assessment." (PMID 33263643, 2020). "The present study aimed to evaluate whether circulating C-reactive protein (CRP) levels are a biomarker of systemic inflammation and a significant predictor of future chronic obstructive pulmonary disease (COPD) outcome." (PMID 24396422, 2014). "Moreover serum angiogenin concentrations were not in correlation with any of the clinical variables as for example: CRP, WBC, tumour size, stage of the disease, chronic obstructive lung disease (COPD), etc." (PMID 23412843, 2012). "COPD, chronic obstructive pulmonary disease; CRP, C-reactive protein; TKA, total knee arthroplasty; THA, total hip arthroplasty." (PMID 28530888, 2017). "A double-blind randomized controlled trial investigated the effects of doxycycline on systemic inflammatory markers (cytokines and C-reactive protein) and neutrophil-specific markers, including MPO in the sputum of patients with stable chronic obstructive pulmonary disease (COPD)." (PMID 36421487, 2022). "High-sensitivity C-reactive protein (hs-CRP) is a known marker of systemic low-grade inflammation in many chronic disorders, including inflammatory bowel disease (IBD), cardiovascular disease, depression and chronic obstructive pulmonary disease (COPD)." (PMID 35010890, 2021). "CRP is not specific to cancer and its impact on survival is not limited to neoplastic diseases, but is observed in cardiovascular disease, osteoporosis, diabetes mellitus, COPD (chronic obstructive pulmonary disease), and generally in all age-related diseases." (PMID 39062127, 2024). "Temperature change could also affect the concentrations of inflammatory markers, such as C-reactive protein, fibrinogen, and interleukin-6 (IL-6), which induces non-infectious respiratory diseases (NIRD), such as asthma and chronic obstructive pulmonary disease (COPD)." (PMID 34063510, 2021).
Thrombocytosis (260 papers, 2005 to 2026). Increased numbers of platelets in the peripheral blood. "Thrombocytosis was associated with clinically and radiologically advanced disease, and platelet count correlated with CRP and erythrocyte sedimentation rate (ESR) values in pulmonary TB patients but not in patients with community acquired pneumonia." (PMID 34093524, 2021). "Inflammatory conditions are a common cause of thrombocytosis and are related to an elevated C-reactive protein or accelerated sedimentation rate as well as elevated pro-inflammatory cytokines such as interleukin-6 (IL-6) and interleukin-11 (IL-11)." (PMID 34945099, 2021). "The results of this study indicate that high platelet count is associated with elevated mGPS and serum CRP levels, supporting the role of thrombocytosis in cancer associated systemic inflammation." (PMID 31196200, 2019). "Patients with elevated serum C-reactive protein levels seem to be at higher risk of developing thrombi, as are those with thrombocytosis." (PMID 22040382, 2011). "However, alternative mechanisms such as subclinical inflammation (e.g., elevated CRP) or iron deficiency (e.g., reduced ferritin) could theoretically contribute to thrombocytosis." (PMID 40917366, 2025). "An elevated number of white blood cells (≥10 G/L) was found in 30 patients (35.7%), elevated serum C-reactive protein (≥5 mg/L) was found in 53 patients (63.1%), and thrombocytosis (PLT count ≥ 450 G/L) was found in 5 patients (5.9%)." (PMID 41156107, 2025). "Biological symptoms include C-reactive protein (CRP) increase, neutrophilia, with occasional leukemoid reactions, thrombocytosis, and inflammatory anemia." (PMID 39754984, 2025). "Laboratory results were consistent with inflammation (ESR 83, CRP 203 (ref. value (RV) < 5 mg/dl), ferritin 311 (RV < 120 μg/L), microcytic anemia, thrombocytosis." (PMID 41374458, 2025). "In KD, the leukocyte count is characterized by neutrophilia and lymphopenia with elevated levels of C-reactive protein and erythrocyte sedimentation rate, thrombocytosis, and elevated levels of alanine aminotransferase and aspartate aminotransferase." (PMID 40303414, 2025). "Circulating TPO concentrations have been shown to correlate with C-reactive protein levels, further supporting the link between systemic inflammation and thrombopoietin-driven thrombocytosis." (PMID 41552126, 2025). "Higher levels of ESR and/or CRP concentrations at onset, thrombocytosis, lower hemoglobin and a more severe course were common findings in many studies." (PMID 40508840, 2025). "For patients aged 40-49 years, PPVs ≥3% were observed for thrombocytosis, low albumin and haemoglobin, and raised alkaline phosphatase and C reactive protein, and in men for raised erythrocyte sedimentation rate and white cell count." (PMID 39414353, 2024). "Thrombocytosis, low albumin and haemoglobin, and raised C reactive protein in younger men also had PPVs ≥3%." (PMID 39414353, 2024). "She presented with thrombocytosis and elevated CRP and indicated prior facial cellulitis that was treated with oral antibiotics." (PMID 38296895, 2024). "It has also been reported that the presence of IL-6 and high CRP in the liver triggers thrombocytosis and IL-6 induces differentiation from megakaryocytes to platelets and leads to an abnormal inflammatory response." (PMID 38218876, 2024). "Low haemoglobin, lymphadenopathy, thrombocytosis, low albumin, and raised C reactive protein in younger men also had PPVs of ≥3%." (PMID 39414353, 2024). "Blood abnormalities included mild thrombocytosis (512,000, reference range 160,000–500,000), alanine aminotransferase increase (1506 U/L, reference range 15–65 U/L), and inflammation (C-reactive protein: 6.6 mg/dL, reference range 0–0.85 mg/dL)." (PMID 37628692, 2023). "Alongside the standard predictors (C°, WBC, CRP, and ESR), the present study made the serendipitous finding that thrombocytosis is frequently present during OAIs caused by K. kingae." (PMID 37763974, 2023).
Thrombocytosis (continued). "Due to persistent inflammatory activity, elevated C-Reactive Protein, thrombocytosis, progressive increase in aneurysm size, treatment was escalated to 3 plasmapheresis sessions." (PMID 36096831, 2022). "Numerous observational studies report thrombocytosis in patients with TB and, in some, platelet count correlated with levels of acute phase reactants such as C-reactive Protein (CRP) and with disease severity." (PMID 34093524, 2021). "TB is associated with thrombocytosis, which is related to the intensity of the inflammatory response; the extent of thrombocytosis can be monitored as an inflammatory marker, such as the erythrocyte sedimentation rate and serum C-reactive protein." (PMID 34361913, 2021). "Laboratory findings showed an elevated ESR of 60 mm and CRP of 48 mg/L and thrombocytosis (458 × 10^9/L)." (PMID 33715142, 2021). "“Inflammaging” is characterized by immunosenescense and thrombocytosis, as well as overproduction of systemic inflammatory cytokines IL-1, TNFα, IL-6, and C-reactive protein (CRP)." (PMID 34502021, 2021). "Typical manifestations included elevation of C-reactive protein, erythrocyte sedimentation rate, leukocytosis, increased immature neutrophil and thrombocytosis." (PMID 34222140, 2021). "During hospitalization some male patients developed mild thrombocytosis and exhibited increased inflammation evaluated in term of high CRP values." (PMID 33858472, 2021). "A report found that thrombocytosis and C-reactive protein influenced pancreatic cancer patient prognosis." (PMID 32393273, 2020). "Laboratory studies revealed thrombocytosis 485,000 cells/mm3 (normal range 130,000–400,000 cells/mm3), elevated C-reactive protein (CRP) 75 mg/dl (normal range 0.1–1.0 mg/dl), and erythrocyte sedimentation rate (ESR) 40 mm/h (normal range 0–20 mm/h)." (PMID 31036083, 2019). "Laboratory tests typically reveal elevation of the acute-phase proteins (ESR, CRP), a complement consumption (in immunocomplex vasculitides), leuko-and thrombocytosis and hypochromic anemia." (PMID 33324879, 2019). "Among SPIROMICS participants who had platelet count and CRP measured at baseline (n = 1041) participants with thrombocytosis had significantly higher median CRP (4.6 vs. 3.0, p = 0.01)." (PMID 29373977, 2018). "After 2 months, his ESR improved from 66 mm/h to 11 mm/h, his CRP improved from 8.4 mg/dL to less than 0.5 mg/dL, his microcytic anemia and thrombocytosis resolved, and his thickened skin normalized." (PMID 29041934, 2017). "The study was aimed to explore the clinical application of particularly mean platelet volume (MPV), hemoglobin, red blood cell indices, white blood cell, serum iron profile, and C-reactive protein level in the differential diagnosis of thrombocytosis." (PMID 22997499, 2012). "The study was designed to evaluate the clinical application of mean platelet volume (MPV), hemoglobin (Hb), red blood cell indices, white blood cell (WBC), serum iron profile, and C-reactive protein (CRP) level in the differential diagnosis of thrombocytosis." (PMID 22997499, 2012). "Laboratory tests show a marked inflammatory response with leukocytosis (neutrophilia), thrombocytosis, high C-reactive protein (CRP) and erythrocyte sedimentation rate (ESR)." (PMID 22611516, 2012). "The main abnormal laboratory findings were decreased hemoglobin (37%), raised ESR and CRP level (36%) and thrombocytosis (>400,000) in 22% of the patients." (PMID 19568575, 2009). "Blood tests revealed a raised white cell count of 20.1 × 109/L and CRP at 185 mg/L, and a thrombocytosis of 641 × 109/L." (PMID 18358077, 2008). "Blood tests showed a raised white cell count of 11.5 × 109/L (NR 4–11) and C-reactive protein (CRP) of 29.6 mg/L (NR 0–5) and a thrombocytosis of 566 × 109/L (NR 150–400)." (PMID 18358077, 2008).